GPX1 (glutathione peroxidase 1)
Diseases named in the same sentence as GPX1 in open-access papers (continued):
Sharing a sentence is not in itself a finding about the gene and the disease.
atherosclerosis (continued). "The GPx-1 enzyme is abundant in endothelial cells and macrophages; therefore, the decreased activity is expected to increase the sensitivity of the vessels to oxidative stress and will be more prone to oxidative stress-induced atherosclerosis." (PMID 35138466, 2022). "Compared to wildtype mice, ApoE mice on a normal chow diet have increased aortic expression of many antioxidant enzymes, including GPx1, GPx3, GPx4 and Txnrd prior to the development of atherosclerosis, but during lesion development, the expression of these antioxidant enzymes declines." (PMID 34579115, 2021). "A more aggressive atherosclerosis has been reported in double knockout (ApoE−/−) (GPx-1−/−) mice compared to (ApoE−/−) controls, with a marked increase in ROS levels and a decrease in NO bioavailability, which was associated with increased protein nitration within the atherosclerotic lesions." (PMID 32630452, 2020). "GPx1 exerts its antioxidant effect to protect the cells from oxidative damage by reduction of lipid peroxidation and clearance of free radicals in the progression of atherosclerosis." (PMID 29518145, 2018). "Several clinical evidences suggest a potential anti-atherogenic role for GPx1 in atherosclerosis." (PMID 29113088, 2017). "Therefore, in ATX mice at this young age corresponding to the early stages of atherosclerosis, skeletal muscle antioxidant enzymes are up-regulated except for Gpx1." (PMID 27010651, 2016). "By contrast, mice with higher level ROS than WT mice due to the defect in a ROS metabolizing enzyme, glutathione peroxidase-1 (GPx-1), are resistant to immune-mediated inflammatory diseases, such as allergen-induced airway inflammation and high fat diet-induced atherosclerosis." (PMID 24743300, 2014). "Recent findings also indicate that the lack of GPx1 contributes to the risk of atherosclerosis and cardiovascular disease." (PMID 24683439, 2014). "The present study demonstrates that GPx-1 deficiency has a significant impact on macrophage foam cell formation and proliferation via the p44/42 MAPK (ERK1/2) pathway encouraging further studies on new therapeutic strategies against atherosclerosis." (PMID 23991041, 2013). "Further study could reveal a possibility of intervention to prevent atherosclerosis among T2D patients by adding sufficient activity of GPx-1." (PMID 17825092, 2007). "Therefore, GPx1 can be considered as a putative target of S-sulfhydration in atherosclerosis." (PMID 29518145, 2018). "Nrf2-regulated genes such as heme oxygenase (decycling) 1 (HMOX1), peroxiredoxin (PRDX1), glutathione peroxidase 1 (GPX1), glutamate-cysteine ligase modifier subunit (GCLM) and NADPH quinine oxidoreductase 1 (NQO1) have been implicated in the protection against atherosclerosis and oxidative stress." (PMID 29113088, 2017). "In conclusion, our present study demonstrates that GPx-1 deficiency has a significant impact on macrophage foam cell formation and proliferation via the p44/42 MAPK (ERK1/2) pathway encouraging further studies on new therapeutic strategies against atherosclerosis." (PMID 23991041, 2013). "Since increased IMT values are positively related with the onset of atherosclerosis, authors concluded that incidence of CVD was higher in a group of patients with GPx-1 Pro/Leu genotype, which is also consistent with obtained values of IMT measurement." (PMID 31210841, 2019). "For instance, GPX1 is a potential antioxidant enzyme with a significant role in the detoxification of lipid hydroperoxides and H2O2, while GPX4 reduces oxidative stress and thus, inhibits atherosclerosis." (PMID 34419016, 2021). "Additionally, the lack of an antioxidative enzyme like GPx-1 accelerates and alters the progression of atherosclerotic lesions, particularly in ApoE−/− mice, emphasizing the significant role of oxidative stress in the pathophysiology of atherosclerosis." (PMID 40227195, 2025).
Obesity (34 papers, 2010 to 2025). Accumulation of substantial excess body fat. "Several SNP variations associated with obesity and insulin resistance have been described so far, especially GPx1 and GPx7 genes." (PMID 40428311, 2025). "Gpx1 knockout (Gpx1−/−) with associated increased ROS production led to enhanced insulin signalling and protected mice from high-fat diet-induced obesity and metabolic impairment." (PMID 37238003, 2023). "A number of single-nucleotide polymorphisms (SNPs) in the GPx1 gene have been associated with obesity, a higher prevalence of MetS, IR, and susceptibility to T2D." (PMID 35740085, 2022). "GPX1 rs1800668 had an increased risk of obesity under homozygote comparison (G/G vs. A/A: OR = 2.65, 95%CI = 1.11–6.32, p = 0.048) and recessive models (G/G vs. A/A-A/G: OR = 2.63, 95%CI = 1.12–6.18, p = 0.024)." (PMID 33924357, 2021). "Reduced levels of glutathione peroxidase-1, the enzyme involved in antioxidation, was suggested to cause fatty liver in the offspring of mothers with obesity." (PMID 34977107, 2021). "Too much data regarding the association between obesity and GPx1, GPx3, GPx4, and GPx7 has been reported." (PMID 29132311, 2017). "Several SNPs of the NRF2 gene have repercussions on certain antioxidant enzymes, for example, rs2234694 is related to SOD1, rs2536512 to SOD3, rs1056806 to GSTM1, rs4880 to SOD2 and rs1800668 to GPx1; all were found in obese patients and were associated with increased risk of obesity." (PMID 40428311, 2025). "Previous studies have reported associations of SNPs SOD2 rs4880, GPX7 rs835337, GPX1 rs1050450, CAT rs1001179 with obesity, body mass index and body fat in Brazilian, Mexican, British, Finnish, Chinese, Caucasian, and African–American adult populations." (PMID 40867795, 2025). "In previous studies, the SNPs SOD2 rs4880, GPX7 rs835337, GPX1 rs1050450, and CAT rs1001179 have been associated with lipid peroxidation, obesity, and their metabolic complications in adult populations." (PMID 40867795, 2025). "A total of 1675 children with normal weight and 1271 children with obesity were included to assess the association of four SNPs, SOD2 rs4880, GPX7 rs835337, GPX1 rs1050450, and CAT rs1001179, with obesity." (PMID 40867795, 2025). "Many of the identified CpGs are located in open sea regions, are often close to obesity-related genes such as GPX1 and LGR4 and altogether, are enriched in cancer and oxidative stress pathways." (PMID 36446949, 2022). "While the GPX gene cluster includes eight types (GPX1-8), the GPX1 and GPX4 variants were associated previously with obesity or related comorbidities." (PMID 33924357, 2021). "Gpx1-deficient epididymal adipocytes were also found to have lower diameter despite normal differentiation status (PPARγ, AP2, and C/EBP), being in agreement with the overall resistance of Gpx1−/− mice to diet-induced obesity." (PMID 32344656, 2020). "In GPx-1 overexpressing mice, increases of GPx-1 activity, ranging from 31 to 300%, were related to obesity and IR, and phosphorylation of Akt was reduced in response to insulin." (PMID 28981461, 2017). "The 5’UTR GPX1 rs1800668*A allele was more prevalent in our obese cohort than non-obese one and showed association with obesity risk under homozygous comparison and recessive models." (PMID 33924357, 2021). "Four SNPs were associated with higher obesity risk under heterozygote and dominant models for GSTM1 rs1056806 (C/T), homozygote model for SOD2 rs4880 (A/G), and homozygote and recessive models for GPX1 rs1800668 (A/G)." (PMID 33924357, 2021). "Moreover, both troglitazone (TZD) treatment and obesity decreased GPX1 and GPX3 protein levels in adipose tissue, being indicative of low contribution of adipose tissue GPX to serum GPX activity." (PMID 32344656, 2020). "GPX1 Pro200Leu polymorphism (rs1050450) was also shown to be associated with morbid obesity, but not (pre)diabetes in obesity in a Mexican population." (PMID 32344656, 2020).
Obesity (continued). "The initial studies that investigated obesity and hyperinsulinemia in GPx1 overexpressing mice only utilized male mice, thus it is unknown whether the effect of GPx1 overexpression in mice is sex-specific." (PMID 26861388, 2016). "The identification of SOD2 rs4880 AA or GPX1 rs1050450 GA + AA carriers may support targeted interventions based on diet and physical activity to promote the non-enzymatic antioxidant response and contribute to mitigating oxidative stress and preventing metabolic complications related to obesity." (PMID 40867795, 2025). "We aimed to assess the direct and modulatory effects of SNPs in antioxidant genes (SOD2 rs4880, GPX1 rs1050450, GPX7 rs835337, CAT rs1001179) on the relationships among obesity-related oxidative stress markers in Mexican children." (PMID 40867795, 2025). "In the present study, we investigated the direct and modulatory effects of four antioxidant enzyme SNPs (SOD2 rs4880, GPX1 rs1050450, GPX7 rs835337, and CAT rs1001179) on the relationships among obesity-related oxidative stress markers in Mexican children." (PMID 40867795, 2025). "HFD-induced obesity lowers the GPX3 plasma concentration in mice and GPX1 expression in the liver and reduces serum glutathione." (PMID 36831188, 2023). "Inheritance association models revealed that four SNPs to have a prediction value for developing obesity, namely GSTM1 rs1056806 (C/T), SOD2 rs4880 (A/G), SOD3 rs2536512 (A/G), and GPX1 rs1800668 (A/G)." (PMID 33924357, 2021). "Our data evidence that sTAC and TBARS are associated with obesity, showing a negative relationship in Mexican children who are non-carriers of SOD2 rs4880 and GPX1 rs1050450." (PMID 40867795, 2025). "Therefore, the present study aims to investigate both the direct and modulatory effects of four SNPs in antioxidant genes (SOD2 rs4880, GPX1 rs1050450, GPX7 rs835337, CAT rs1001179) on the relationships among obesity-related oxidative stress markers in Mexican children." (PMID 40867795, 2025). "Interestingly, and in contrast to the current findings on NPGx, absence of GPx1, another member of the NPG family, which likewise is a sensor and transducer of ROS signalling leads to a protection from obesity and the associated metabolic disorders." (PMID 23918226, 2013).
prostate carcinoma (24 papers, 2012 to 2024). A carcinoma that arises from epithelial cells of the prostate gland. "This is consistent with the results of a prospective study in European men, where individuals with the CT/TT allele of GPX1 rs1050450 showed a protective effect of serum selenium on prostate cancer." (PMID 37765058, 2023). "Functional SNP rs1050450 in the GPX1 gene has been previously investigated in association with the risk of prostate cancer development." (PMID 36295574, 2022). "In a Macedonian population, the GPx1 Pro198Leu genotype showed an overall protective effect on prostate cancer risk, and erythrocyte GPx1 activities were significantly decreased in prostate cancer patients compared with controls." (PMID 32571353, 2020). "The EPIC-Heidelberg nested prostate cancer case-control study indicates that men with the variant T allele of the GPX1 rs1050450 polymorphism record a risk ratio (odds ratio OR) of 0.87 per 10 ng/mL increase in serum selenium." (PMID 31861307, 2019). "Quantification of GPX1 levels in the entire cell, the cytoplasm, and the nucleus did not indicate any association of either its levels or subcellular distribution with prostate cancer recurrence." (PMID 30453672, 2018). "GPX1 levels are responsive to selenium availability and previous studies have reported an inverse relationship between selenium nutritional status and prostate cancer risk." (PMID 30453672, 2018). "Previously, the samples had been analysed for six selenoprotein SNPs and rs1053040 in GPX1 was found to modulate the effect of serum Se on prostate cancer risk." (PMID 23133653, 2012). "The earlier data showed that genotype for rs1050450 in GPX1 modified association of serum Se concentration with prostate cancer risk." (PMID 23133653, 2012). "The aim of our study was to investigate the possible role of functional polymorphisms of antioxidant enzymes SOD2 and GPX1 and regulatory antioxidant protein Nrf2, alone or combined, in susceptibility to prostate cancer development and overall survival in Serbian male patients." (PMID 36295574, 2022). "Several studies have examined whether polymorphisms in the GPX1 gene were associated with prostate cancer risk, and the results have been mixed." (PMID 30453672, 2018). "This is the first study to our knowledge that examined whether prostate cancer recurrence was associated with levels of the GPX1 protein." (PMID 30453672, 2018). "For these reasons, GPX1 was imaged in prostate tissue and cell lines, and it was assessed whether GPX1 levels were associated with prostate cancer recurrence after prostatectomy." (PMID 30453672, 2018). "This was done by quantifying the GPX1 levels in tissue cores obtained from 200 prostate cancer patients who experienced biochemical recurrence (rising PSA levels) and 200 matched control patients whose cancers did not return, by immunohistochemistry." (PMID 30453672, 2018). "The changes in activity of GPX1, GPX2, and GPX3 isoforms may be associated with the development of cancers, for example, prostate cancer or even colon cancer." (PMID 26682223, 2015). "These earlier studies have provided evidence that variants in a combination of the SEPP1 and manganese superoxide dismutase (SOD2) genes affects disease risk, that rs1050450 in GPX1 affects the influence of Se status on risk and that variants in SEP15 affect prostate cancer survival." (PMID 23133653, 2012). "Such a relationship was observed between the rs1050450 polymorphism of the GPX1 gene (glutathione peroxidase 1) and the following neoplasms: breast, prostate, bladder and lungs and the rs7579 polymorphism of the SEPP1 gene (selenoprotein P1) with colorectal and prostate cancer." (PMID 35205233, 2022). "Several lines of evidence have indicated that GPX1 may be relevant to prostate cancer etiology." (PMID 30453672, 2018).
prostate carcinoma (continued). "GPX3 gene codes for the Glutathione peroxidase 3, also known as plasma glutathione peroxidase (GPx-P), the variations in activity of GPX1, GPX2, and GPX3 isoforms may be associated with the development of cancers, for example, prostate cancer or even colon cancer." (PMID 27874091, 2016). "Also, SNPs in MnSOD, GPX1, GPX4, CAT were found to be associated with prostate cancer." (PMID 26301412, 2015). "Thus overall, the data from this EPIC-Heidelberg nested case-control study indicate that together Se status and GPX1, SEPP1, TXNRD1, TXNRD2, and SELK genotype significantly alter risk of high-grade or advanced stage prostate cancer in a population with suboptimal Se intake." (PMID 23133653, 2012). "For example, GPX1, SELENOF, and SELENOP levels were significantly reduced in prostate cancer models, whereas GPX2 was significantly increased." (PMID 32933107, 2020). "Given the data presented above indicating nuclear localization of GPX1 in primary or immortalized prostate cells but not in cancer-derived cell lines, we assessed whether GPX1 levels or sub-cellular location was associated with prostate cancer recurrence following a prostatectomy." (PMID 30453672, 2018). "Additionally, research investigating the mRNA profile of DU145 cells treated with sodium selenite observed an increased expression of GPX1, GPX2, and GPX4 and a decreased expression of TXNRDs in prostate cancer." (PMID 37765058, 2023). "Given the unexpected location of GPX1 in the nucleus of prostate epithelium, the subcellular location of GPX1 was determined by immunofluorescence in primary prostate cells, the RWPE-1 immortalized prostate epithelial cell line, and the LNCaP and PC3 human prostate cancer-derived cell lines." (PMID 30453672, 2018). "In conclusion, this study as well as our previous genetic studies on MTHFR in breast and prostate cancer, EGFR in lung cancer, and GPX-1 in bladder cancer is an important contribution in order to integrate pharmacogenetics in clinical practice in Ecuador and Latin America." (PMID 30065942, 2018). "While GPX1 levels may not have an impact on survival among men with prostate cancer, the data indicates that this extensively characterized protein may have a novel function in the nucleus of prostate epithelial cells." (PMID 30453672, 2018). "In contrast, GPX1 was localized to the cytoplasm of LNCaP and PC3 human prostate cancer-derived cells with no apparent nuclear staining." (PMID 30453672, 2018).